LDLRAD1 (low density lipoprotein receptor class A domain containing 1)
Tractability: Antibody: UniProt predicts a signal peptide or a membrane-spanning region.
Gene: Protein-coding gene on chromosome 1 (54,007,298 to 54,018,194, reverse strand). Ensembl gene ENSG00000203985.
Subcellular location: Membrane
Subcellular location (Human Protein Atlas): Nucleoplasm; Golgi apparatus; Primary cilium
Gene Ontology:
Molecular function: protein binding
Biological process: vesicle-mediated transport
Cellular component: membrane
Genetic constraint (gnomAD): Loss-of-function variants: 21 observed, 26.48 expected, observed/expected ratio (o/e) 0.79, 90% interval 0.56 to 1.14. The upper end of that interval is the gene's LOEUF score, 1.14, which puts it in group 5 of 6, group 1 being the genes least tolerant of losing a copy. Missense variants: 277 observed, 270.01 expected, observed/expected ratio (o/e) 1.03, 90% interval 0.93 to 1.13. Synonymous variants: 103 observed, 107 expected, observed/expected ratio (o/e) 0.96, 90% interval 0.82 to 1.13.
Homologues: Orthologues: chimpanzee LDLRAD1 (99% identical), macaque LDLRAD1 (91% identical), rabbit LDLRAD1 (81% identical), dog LDLRAD1 (80% identical), guinea pig LDLRAD1 (76% identical), mouse Ldlrad1 (72% identical), rat Ldlrad1 (70% identical), pig LDLRAD1 (65% identical), tropical clawed frog ldlrad1 (41% identical), Drosophila melanogaster loaf (25% identical).
Diseases named in the same sentence as LDLRAD1 in open-access papers:
LDLRAD1 is named in the same sentence as 5 diseases in open-access papers, as found by Europe PMC text mining. Sharing a sentence is not in itself a finding about the gene and the disease. The quoted sentences say what the papers report.
breast carcinoma (2 papers, 2013 to 2020). "Little is known about LDLRAD1, with most marked gene expression in lung and fallopian tube, and a rare variant in this gene has been associated with breast cancer." (PMID 33186364, 2020). "One association for breast cancer, a single SNP in LDLRAD1, appeared to pass our established level of global significance (p<3.9×10−7) when all cases were examined." (PMID 23555315, 2013). "In breast cancer, the strongest associations included either SNPs in or gene burden scores for genes LDLRAD1, SLC19A1, FGFBP3, CASP5, MMAB, SLC16A6, and INS-IGF2." (PMID 23555315, 2013).
prostate carcinoma (1 paper, 2013). A carcinoma that arises from epithelial cells of the prostate gland. "However, only one of the associations (rs145889899 in LDLRAD1, p = 2.5×10−7 only seen in African Americans) for overall breast or prostate cancer risk was statistically significant after correcting for multiple comparisons." (PMID 23555315, 2013).
bacterial infection (1 paper, 2023). "Finally, LDLRAD1 is known to be potentially involved in resistance against bacterial infection, while RBM39 has been proposed as target of putative selective sweep in swine being involved in RNA splicing and RNA processing." (PMID 37605116, 2023).
cardiovascular disease (1 paper, 2020). "We identified one known locus (ANGPTL4) and four new loci (PLCL1, RC3H2, TMPRSS5, and LDLRAD1) associated with cardiovascular disease risk that warrant further investigation." (PMID 33186364, 2020). "This study identified one known locus (ANGPTL4) and four new loci (PLCL1, RC3H2, TMPRSS5, and LDLRAD1) associated with cardiovascular disease risk that warrant further investigation." (PMID 33186364, 2020).
LDLRAD1 also shares sentences with these, for which no sentence is quoted: Epileptic encephalopathy (1 paper).